STAT3 (signal transducer and activator of transcription 3)
Diseases named in the same sentence as STAT3 in open-access papers (continued):
Sharing a sentence is not in itself a finding about the gene and the disease.
breast cancer (continued). "For example, FABP1 enhances mitochondrial β-oxidation in hepatocellular carcinoma to provide energy, while FABP4 promotes breast cancer cells to take up fatty acids from adipocytes and activates the STAT3 pathway to drive epithelial-mesenchymal transition (EMT)." (PMID 40717587, 2025). "However, in breast cancer, STAT3 is a known driver of chemoresistance, EMT, and metastasis, where it transcriptionally regulates genes involved in these processes." (PMID 40507264, 2025). "Moreover, ATB in breast cancer cell also enhances stemness and invasiveness through activating STAT3 the STAT3 pathway." (PMID 39912983, 2025). "This flavanone was found to inhibit breast cancer stem cells through the inhibition of colony and mammosphere formation, reduced levels of transcriptional factors (Oct2, Nanaog, Sox2), and the inhibition of STAT3 signaling pathways." (PMID 39859345, 2025). "It promotes malignant transformation by activating the STAT3 signaling pathway, thereby regulating genes involved in cell cycle progression and survival, and its expression is positively correlated with advanced clinicopathological features of breast cancer." (PMID 40969325, 2025). "Conversely, knocking down STAT3 increased ROS production in breast cancer cells." (PMID 40386046, 2025). "This suggests that melatonin inhibits STAT3-mediated paclitaxel resistance in breast cancer." (PMID 40843360, 2025). "Altogether, our data suggests that the crosstalk between APE1 and STAT3 is critically for breast cancer survival and aggressiveness, and their inhibition could be promising for the development of future therapies." (PMID 41090323, 2025). "Notably, STAT3 exhibits abnormal activation in several types of cancer cells, such as those found in breast cancer, prostate cancer, head and neck cancer, colon cancer, lung cancer and multiple myeloma." (PMID 40563476, 2025). "In addition, inhibiting JAK/STAT3 blocked self-renewal of breast cancer stem cells and expressions of diverse lipid metabolic genes, including FAO-related genes." (PMID 40882371, 2025). "A previous study reported that C15:0 could suppress IL-6-induced JAK2/STAT3 signaling in MCF-7/stem-like breast cancer cells." (PMID 40356914, 2025). "However, the potential of IL6 to induce and maintain EMT in breast cancer cell lines depends on activation of the JAK/STAT3 pathway." (PMID 40141419, 2025). "In conclusion, we found that circRNA-14,052 could promote the progression of breast cancer via the miR-214-3p/IKBKB/IL6/JAK/STAT3 axis." (PMID 41044672, 2025). "In addition, a large number of studies have confirmed that JAK2/STAT3 signaling plays an important role in breast cancer progression, regulating key processes including cell proliferation, survival and immune escape." (PMID 40351419, 2025). "The role of STAT3 in HER2-positive breast cancers is controversial." (PMID 40507264, 2025). "HA-CD44 interaction enhances breast cancer MDR by regulating MDR1 through the STAT3 pathway." (PMID 40843360, 2025). "Thus, we suggest the APE1 redox domain and STAT3 as promising targets for new therapy strategies against breast cancer." (PMID 41090323, 2025). "Therefore, we selected the cervical cancer cell line HeLa and the breast cancer cell line MCF-7 as models to investigate the impact of the six D-PROTACs on STAT3 protein degradation." (PMID 40118821, 2025). "Baseline table of STAT3 gene high and low expression groups in breast cancer." (PMID 40636126, 2025). "The activation of the STAT3 pathway could promote proliferation, invasion, metastasis, and angiogenesis, while inhibiting apoptosis in breast cancer cells." (PMID 40830747, 2025). "MH-mediated inhibition of p-STAT3 has been reported in lung and breast cancer cell lines." (PMID 40059876, 2025). "STAT3 polymorphisms have been reported in breast cancer but were either not significant in tumorigenesis or were controversial." (PMID 40507264, 2025).
breast cancer (continued). "While these are only some examples, STAT3 transcriptional activity is highly involved in breast cancer tumorigenesis, and identifying important STAT3 target genes will aid in better understanding the role STAT3 plays in breast cancer." (PMID 40507264, 2025). "Therefore, the objective of this study was to evaluate the effects of ADSC-derived extracellular vesicles on MCF-7 breast cancer cells, with a focus on cell viability, migration, IL-6/STAT3 signaling, and cytoskeletal structure." (PMID 41514893, 2025). "STAT3 is also involved in various signaling pathways that contribute to breast cancer progression, promoting proliferation, inhibiting apoptosis, supporting angiogenesis and metastasis, and conferring resistance to breast cancer therapy." (PMID 40608162, 2025). "Summary table of STAT3 target genes and cofactors in breast cancer." (PMID 40507264, 2025). "That agrees with what has been reported earlier, where BCP-oxide was found to reduce STAT3 level in MM, prostate and breast cancer cell lines via upregulation of the tyrosine phosphatase, SHP-1, and by inhibiting the kinases, JAK1/2, and their downstream target, STAT3." (PMID 40333803, 2025). "Furthermore, breast cancer cases that had concurrent activation of STAT3 and STAT5 were more likely to be well differentiated and associated with a more favorable prognosis and tumor type." (PMID 40507264, 2025). "Additionally, a study has shown that IL-22 released by Th17 cells can activate the MAP3K8 signaling pathway in BC cells, which in turn activates the STAT3 and AP-1 pathways, thereby increasing breast cancer aggressiveness." (PMID 41597595, 2025). "Inhibitors targeting FTO or STAT3 can reduce doxorubicin resistance, which may be a potential therapeutic strategy for breast cancer." (PMID 40483535, 2025). "In this study, we first reported that APX2009 impairs STAT3 transcriptional activity in breast cancer cells, leading, in combination with Stattic, to a further decrease in the survival and aggressiveness of breast cancer cells in vitro, compared to treatments alone." (PMID 41090323, 2025). "BO can decrease the expression of STAT3 in human breast cancer cell lines." (PMID 40076902, 2025). "Moreover, curcumin has been widely investigated for its potential therapeutic benefits in breast cancer, especially through its influence on the STAT3 signaling pathway." (PMID 41020838, 2025). "APE1 and STAT3 are highly expressed in cancers such as pancreatic, ovarian, and breast cancer." (PMID 41090323, 2025). "Since constitutive STAT3 is often associated with TNBC and other aggressive breast cancer subtypes that currently lack effective therapies, using STAT5 to modulate STAT3 activity could be an interesting avenue to pursue." (PMID 40507264, 2025). "Notably, IL-6/STAT3 signaling can induce a cancer stem cell phenotype: IL-6 drives the expansion of breast cancer stem-like cells by upregulating stemness factors and maintaining an undifferentiated, therapy-resistant state." (PMID 41007766, 2025). "Our findings furthermore suggest that genotoxic agents in combination with STAT3/FA-BRCA pathway inhibitors could be an effective treatment for breast cancers." (PMID 40038300, 2025). "Additionally, STAT3 activation in cancer-associated fibroblasts increases the secretion of ANGPTL4 into the tumor microenvironment, promoting breast cancer progression in vivo and enhancing invasion and migration in breast cancer cells." (PMID 40723247, 2025). "In addition, a high level of serum resistin has been reported to be correlated with poor overall survival of patients with breast cancer, which is caused by the activation of Toll-like receptor 4 (TLR4)/NF-κB/STAT3 signaling pathway." (PMID 40863244, 2025). "STAT3 can drive resistance to targeted therapies in breast cancer through alternative pathways." (PMID 40949156, 2025).
breast cancer (continued). "Given that key stemness-related pathways—such as Wnt/β-catenin, TGF-β, and STAT3—are conserved across various tumor types, including colorectal and breast cancers, we conducted an in vivo study of stemness inhibitors using the EO771 triple-negative breast cancer mouse model." (PMID 40160820, 2025). "Collectively, circRNA-14,052 knockdown could inhibit the breast cancer progression in vitro via miR-214-3p/IKBKB/IL-6/JAK2/STAT3 axis." (PMID 41044672, 2025). "Avalle and his colleagues found that STAT3 could promote the secretion of ANGPTL4 to accelerate cell growth in breast cancer." (PMID 38212795, 2024). "Furthermore, SchA has shown promise in overcoming doxorubicin resistance in breast cancer cells by inhibiting P63 and Stat3 phosphorylation." (PMID 38376003, 2024). "Although transcription factor YY1 regulates METTL8 expression in breast cancer cells and STAT3 transcriptionally activates METTL8 in mouse embryonic stem cells, the upstream regulator of METTL8 in GBM remains unknown." (PMID 38744809, 2024). "The p27-activated gene profile is over-represented in STAT3 activated human breast cancers." (PMID 38886396, 2024). "STAT3 signaling pathway has been shown to be elevated in breast cancer, particularly TNBC." (PMID 39525621, 2024). "In addition, high expression of STAT3 and IL-6 can reduce chemotherapy sensitivity in high-grade breast cancer." (PMID 39136000, 2024). "STAT3 also binds with FTO promoter to activate its transcription in breast cancer cells." (PMID 38297099, 2024). "More recently, it has been shown that STAT3 may also be asymmetrically dimethylated by histone arginine N-methyltransferase 6 (PRMT6) at arginine 729 (STAT3 R729me2a), increasing the capacity to induce metastasis in breast cancer." (PMID 38534772, 2024). "Aberrant STAT3 phosphorylation is reported in up to 70% of solid and hematologic cancers including multiple myeloma, lymphomas, leukemias, head and neck cancer, and breast cancer." (PMID 38339245, 2024). "MDSCs strongly induce STAT3 phosphorylation in breast cancer cells co-cultured with MDSCs." (PMID 38625901, 2024). "Furthermore, STAT3 regulates aerobic glycolysis by stimulating hexokinase 2 in breast cancer, and upregulating lactate dehydrogenase A (LDHA) in myeloma." (PMID 38245798, 2024). "miR-634 decreases the radio resistance of human breast cancer cells by targeting STAT3." (PMID 38704809, 2024). "This study investigated whether the AM-18002 and RT combination synergistically induced cancer cell death and whether AM-18002 exerted its anticancer effect by inhibiting STAT3-related MDSC generation in FM3A breast cancer cells in vitro." (PMID 38625901, 2024). "Additionally, tGLI1 can functionally interact with signal transducer and activator of transcription 3 (STAT3) in breast cancer." (PMID 39768178, 2024). "Moreover, recent research has demonstrated that CD8+ effector T cells oxidize more fatty acids by the leptin STAT3 axis, which suppresses anti‐tumor immune responses in breast cancer." (PMID 38923758, 2024). "Additionally, it reduced the growth of tumors, downregulated downstream target proteins of STAT3 (such as Jak2, Src, and cyclin D1), and boosted caspase-3 and -9 apoptotic activity in breast cancer." (PMID 38397437, 2024). "In the NIH3T3/v-Src and MDA-MB-435 human breast cancer cell lines that harbor constitutively active STAT3, S3I-M2001 treatment inhibited STAT3-dependent transcriptional regulation of several tumor survival genes, including Bcl-XL and suppressed the growth of human MDA-MB-231 breast tumor xenografts." (PMID 38339245, 2024). "UANFs can indeed inhibit the growth of MCF-7 breast cancer cells, inhibit the expression of phospho-signal transducer and activator of transcription 3 (STAT3) and phospho-extracellular regulated protein kinase (ERK) 1/2, and induce cleaved expression of caspase-3 protein." (PMID 39339184, 2024).
breast cancer (continued). "While LDHC silencing greatly reduced the cell survival of basal-like breast cancer cells via the downregulation of STAT3 signaling, it exerted the opposite effect in Her2-enriched breast cancer cells, which could be reversed by STAT3 inhibition." (PMID 39001513, 2024). "TGLI1 and STAT3 are concurrently activated in HER2-enriched breast cancer and TNBC subtypes." (PMID 39768178, 2024). "In addition, isoliquiritigenin (ISL), xanthoangelol, 4-hydroxyderricin, and xanthohumol contribute to the suppression of STAT3 expression in various cancer cells, including breast cancer, cholangiocarcinoma and pancreatic cancer." (PMID 38686052, 2024). "Moreover, functional assays uncovered the crucial role of CCT2 in breast cancer progression via the JAK2/STAT3 signaling pathway." (PMID 39079960, 2024). "However, breast cancer tissues exhibit a low expression of let-7a, preventing Stat3 translation due to less interaction with the Stat3 3′ UTR promoter." (PMID 38785973, 2024). "Furthermore, in various tumors, including lung cancer, breast cancer, and colorectal cancer, the activation of the CXCL12/CXCR4/ACKR3 signaling axis has been associated with STAT3 pathway activation." (PMID 38920657, 2024). "Furthermore, tangeretin exhibits the potential to inhibit the formation of breast cancer stem cells (BCSCs) by acting on the Stat3/Sox2 signaling pathway, offering a potential therapeutic strategy for breast cancer and BCSCs." (PMID 38998484, 2024). "STAT3 is a key regulator promoting the proliferation of breast cancer stem cells." (PMID 39770571, 2024). "FTO overexpression enhanced the doxorubicin resistance of breast cancer cells by STAT3 pathway." (PMID 38782769, 2024). "Additionally, HOXC10 contributes to breast cancer progression by activating the IL‐6/JAK2/STAT3 signaling axis." (PMID 39558881, 2024). "STAT3 activity was increased in EGFR+ HER2+ breast cancer cells compared to EGFR+ cells." (PMID 39791720, 2024). "MDSCs triggered persistent STAT3 activation and increased the invasiveness of breast cancer cells." (PMID 38625901, 2024). "Furthermore, luteolin has been shown to enhance the sensitivity of MDA-MB-231 breast cancer cells to doxorubicin and paclitaxel by inhibiting Nrf2 signaling and blocking STAT3, respectively." (PMID 39519572, 2024). "TTI-101 is also the only STAT3 inhibitor under clinical investigation for advanced breast cancer as well as HR+/HER2-palbociclib-resistant breast cancer (NCT03195699; NCT05384119) and could be a viable candidate to combine with a tGLI1-targeting agent." (PMID 39768178, 2024). "Methylselenic acid inhibits breast cancer tumor growth by inhibiting JAK2/STAT3 pathway." (PMID 38872110, 2024). "In this study, the exosome-derived lncRNA HAGLROS from breast cancer cells induced TAM/M2 polarization through activation of the p-STAT3 signaling pathway, which in turn promoted breast cancer cell proliferation, migration, invasion, EMT process, and angiogenesis." (PMID 39198393, 2024). "If STAT3 overexpression is more common in a specific subtype of breast cancer, it might serve as an essential indicator for therapy planning and the development of new medications." (PMID 38691208, 2024). "Moreover, CYP3A4 is involved in the synthesis of epoxyeicosatenoic acids (EETs) and facilitates the growth of breast cancer cells via STAT3 activation mediated by EET." (PMID 38297388, 2024). "Its supernatant could inhibit the autocrine secretion of IL-6 and the phosphorylation of JAK2/STAT3 in the breast cancer cell line MCF-758." (PMID 38395948, 2024). "Moreover, a recent study showed that the migration of breast cancer (BC) cells can be enhanced as a result of ATX activation mediated by the transcription factor Stat3 (Signal transducer and activator of transcription 3)." (PMID 39062979, 2024). "Importantly, the co-expression levels of CXCR4 and p-STAT3 in breast cancer tissues were correlated with tumor size, lymph node metastasis and histological grade of breast cancer." (PMID 37497001, 2023).
breast cancer (continued). "In addition, RANTES and proinflammatory cytokines such as IL-6 can produce a more aggressive phenotype in breast cancer cells via AKT or STAT3 signal pathways." (PMID 37298699, 2023). "The downregulation of STAT3 phosphorylation suggests that VaM may inhibit breast cancer growth by modulating the STAT3 signaling pathway." (PMID 37569363, 2023). "Notably, a recent study in YAP/TAZ-bound regions upregulated in breast cancer has detected an increased binding co-occurrence for the orthologs of our key regulatory TFs: AP-1, STAT3, C/EBP, and TEAD (Jra, kay, Stat92E, Sd, Irbp18, slbo)." (PMID 37133250, 2023). "In this study on breast cancer, we also observed increased expression of p-STAT3 and C-MYC, suggesting that Six1's regulation of breast cancer stem cells may also involve the STAT3 signaling pathway." (PMID 38031089, 2023). "Adipocyte-derived IL-6 and leptin promote breast cancer metastasis by activating the Janus kinase (JAK)/signal transducer and activator of transcription 3 (STAT3) and phosphoinositide 3-kinase (PI3K)/protein kinase B (AKT) signaling pathways, thus upregulating lysyl hydroxylase (PLOD2) expression." (PMID 36624542, 2023). "Serotonin has already been shown to affect the proliferation and metabolism of breast cancer cells by triggering two distinct signaling pathways: Jak1/STAT3 which boosts glycolysis by upregulating PKM2, and adenylyl cyclase/PKA which promotes mitochondrial biogenesis." (PMID 37046602, 2023). "In addition, IL-6, VEGF and NF-κB promotes the expression of c-MYC via STAT3, leading to the development of breast cancer invasion and metastasis." (PMID 36721232, 2023). "Recently, it has been demonstrated that THP-1-derived macrophages that were directly exposed to apoptotic breast cancer cells stimulated with hydrogen peroxide or cisplatin released exosomes, which enhanced tumor growth and metastasis by activating the STAT3 pathways." (PMID 36980788, 2023). "Narasin inhibits TGF‐β/SMAD3 and IL‐6/STAT3 activation in breast cancer cells." (PMID 37864240, 2023). "The complexes did not affect the proliferation and cell cycle of 4T1 breast cancer cells but caused a higher inhibition of cell migration and invasion compared with the application of naked STAT3 siRNA." (PMID 38067351, 2023). "In addition to membranous proteins, TRIM-ing of specific PTM forms of STAT3 also resulted in similar cytotoxic effects in breast cancer cells alone, which was further synergized with STAT3 inhibitors like stattic or niclosamide." (PMID 38213543, 2023). "In fact, STAT3 is activated in over 40% of breast cancer patients." (PMID 37173892, 2023). "Accordingly, we investigated whether the EHF expression is correlated with the suppression of the STAT3 signaling pathway in breast cancer cells." (PMID 37958443, 2023). "Activation of JAK2/STAT3 signaling facilitates the growth of breast cancer cells." (PMID 36674719, 2023). "STAT3 is also an essential apoptotic factor in breast cancer." (PMID 38067351, 2023). "Moreover, in patients with breast cancer, a poor radiotherapy response correlated with high IL-6 and p-STAT3 levels." (PMID 36635302, 2023). "However, particles loaded with Chol-DsiSTAT3 had a more tremendous potential to reduce STAT3 on the protein level than Chol-siSTAT3 in 4T1 breast cancer in vivo." (PMID 38067351, 2023). "As mitochondrial DNA polymerase gamma (POLG) is essential for mtDNA replication, we hypothesized that PRRG4 may regulate mtDNA content by controlling POLG expression through STAT3 in breast cancer cells." (PMID 38102641, 2023). "Moreover, the IL-6/STAT3 signaling pathway was highlighted as one of the first potential targets for Manuka honey-induced breast cancer cell suppression." (PMID 36978815, 2023). "Indeed, breast cancer-derived exosomes absorbed by bone marrow cells activate STAT3, leading to CXCR4 reduction." (PMID 38001753, 2023).